CTPS1 (CTP synthase 1)
Diseases named in the same sentence as CTPS1 in open-access papers (continued):
Sharing a sentence is not in itself a finding about the gene and the disease.
cancer (16 papers, 2011 to 2025). A tumor composed of atypical neoplastic, often pleomorphic cells that invade other tissues. "Analysis of public databases of more than 1,000 inactivated cancer cell lines for CTPS1 or CTPS2 confirmed that cell growth is highly dependent on CTPS1 but not or less on CTPS2." (PMID 37348953, 2023). "CTPS1 silencing in TNBC cancer cell lines decreased proliferation, migration, and invasion as well as increased apoptosis." (PMID 35203388, 2022). "Human CTPS1 (hCTPS1), one of the two CTPS isoforms, is essential for immune responses and is highly expressed in proliferating cells, making it a promising therapeutic target for immune-related diseases and cancer." (PMID 40739251, 2025). "Notably, CTPS1 is overexpressed in many cancer cells, and its activity is essential for the replication of viruses, pathogens, and parasites, making it a promising therapeutic target for cancer, infectious diseases, and immune disorders." (PMID 40739251, 2025). "While targeting CTPS1 may offer opportunities to enhance radiosensitivity of cancer patients, challenges related to specificity and off-target effects require further studies." (PMID 40817599, 2025). "However, their potential as anti-cancer agents targeting CTPS1 alone or in combination with other standard-of-care pyrimidine synthesis inhibitors must be further evaluated in vitro and in vivo." (PMID 35203388, 2022). "Importantly, high expression of CTPS1 is associated with resistance to radiotherapy in mouse models and clinical cancer patients, suggesting that the CTPS1 may serve as a potential therapeutic target." (PMID 40817599, 2025). "Thus, the efficacy of a treatment targeting CTPS1 might be particularly dependent on the level of CTPS2 in cancer cells." (PMID 37348953, 2023). "Consequently, selective targeting of CTPS1 with small molecules could be a promising new anti-cancer strategy." (PMID 35203388, 2022). "Recently, there was a renewed interest in generating inhibitors to CTPS activity that selectively target CTPS1 for therapeutic use, to control immune responses, cancer cell proliferation, and viral replication." (PMID 40957650, 2025). "In conclusion, our study is an important contribution to the understanding of the respective roles of CTPS1 and CTPS2 in cell proliferation, in particular in cancer cells, for which limited information is currently available." (PMID 37348953, 2023). "With the discovery of increased levels of CTPS1 in lymphoblastic as well as other cancer tissues compared to the unchanged levels of CTPS2 in malignant and healthy tissue, targeting CTPS1 has received renewed interest only recently." (PMID 35203388, 2022). "Public databases analysis of more than 1,000 inactivated cancer cell lines for CTPS1 or CTPS2 confirmed that cell growth is highly dependent of CTPS1 but less or not of CTPS2." (PMID 37348953, 2023). "CTP synthetase activity is high in proliferating cells including cancer cells; however, the respective roles of CTPS1 and CTPS2 in cell proliferation are not known." (PMID 37348953, 2023). "Taken together, these results extended our observations showing that most of the cancer cell lines tested (>1,000 different cell lines) are highly dependent on CTPS1 but not or less on CTPS2 for their survival and proliferation." (PMID 37348953, 2023). "CTPS1 enzyme inhibitors 6-diazo-5-oxo-L-norleucine and Acivicin as well as the IMPDH2 inhibitor Ribavirin exhibited dose-dependent induction of RR in >95% of cells in all cancer cell lines tested as well as mouse primary cells." (PMID 22220215, 2011). "Studies have demonstrated that CTPS1 and IMPDH2 are aberrantly expressed in different cancers." (PMID 22220215, 2011). "Altogether, the higher activity of CTPS1 may be required in vivo to rapidly meet a critical need of CTP in highly proliferating cells, like activated T lymphocytes or cancer cells, whereas CTPS2, which has a lower activity, may be rather involved in maintaining basal cellular CTP pools in general." (PMID 37348953, 2023).
tumor (10 papers, 2019 to 2025). "We observed that CTPS1 was overexpressed in TNBC tumor tissues and associated with poor prognosis." (PMID 34991621, 2022). "Many studies have shown that CTPS1 promotes the proliferation and migration of tumor cells, thus accelerating the occurrence of tumors." (PMID 39834822, 2024). "Higher CTPS1 expression was closely related with worse clinicopathologic features such as larger tumor size, higher histological grade and lymphovascular invasion." (PMID 34991621, 2022). "Our previous proteomic analysis has uncovered that CTPS1 is significantly highly expressed in TNBC tumor compared with corresponding para-tumor tissues." (PMID 34991621, 2022). "We scored the CTPS1 expression level based on the CTPS1 staining intensity and percentage of positive tumor cells." (PMID 34991621, 2022). "Higher CTPS1 expression was also correlated with larger tumor size (p = 0.023), higher histological grade (p = 0.019) and lymphovascular invasion (p = 0.012)." (PMID 34991621, 2022). "Up to now, few studies have investigated the role of CTPS1 on tumor development and progression." (PMID 34991621, 2022). "In addition, in vivo studies with mouse models revealed that CTPS1 knockdown remarkably reduced the tumor volume and weight." (PMID 34991621, 2022). "Xenograft tumor model also indicated that CTPS1 knockdown remarkably reduced tumor growth in mice." (PMID 34991621, 2022). "The tumor weight was also found to be remarkably decreased in shCTPS1 group after CTPS1 knockdown." (PMID 34991621, 2022). "The tumor volume was drastically suppressed by the inhibition of CTPS1." (PMID 34991621, 2022). "All these data provide evidence that CTPS1 could act as a tumor activator for the growth of TNBC in vivo." (PMID 34991621, 2022). "Furthermore, a reduction in tumor growth was observed in TNBC xenografts upon CTPS1 silencing." (PMID 35203388, 2022). "CTPS1 was one of the highly differently expressed proteins (DEPs) between TNBC tumor and corresponding para-tumor tissues." (PMID 34991621, 2022). "The IHC score of CTPS1 expression was found to be significantly elevated in the TNBC tumor tissues than the noncancerous counterparts." (PMID 34991621, 2022). "Interestingly, uridine (which DESI-MS revealed to have a high relative abundance in the tumor epithelium of pre-NACT PR samples), which serves as a substrate for cytidine 5-prime triphosphate synthetase (CTPS1), was highly abundant in pre-NACT PR samples (logFC 0.97, LIMMA p = 0.008)." (PMID 37923835, 2023).
infection (3 papers, 2021 to 2025). The state of being infected such as from the introduction of a foreign agent such as serum, vaccine, antigenic substance or organism. "Only infection by B95.8 induced MYC, a well characterized regulator of metabolism, as well as CTPS1 by 48 h of infection." (PMID 34281398, 2021). "In agreement with the RNA-seq results, RRM2, CTPS1, and TK1 were significantly expressed after infection with swH1N1 relative to the pigs infected with huH1N1." (PMID 39247193, 2024). "Genes involved in pyrimidine metabolism (RRM2, CTPS1, TK1, NME1, NME2, and UCK2) were induced after infection with swH1N1 compared to huH1N1." (PMID 39247193, 2024). "Conversely, depletion of CTPS1 reduced SARS-CoV-2 RNA abundance by 2-fold for N and E genes and >10-fold for Nsp1 gene, which correlated with a 4-fold reduction in viral titer in the medium at 48 h post-infection." (PMID 40298378, 2025). "RRM2, CTPS1, and TK1 were highly expressed after infection with swH1N1 compared to huH1N1." (PMID 39247193, 2024).
CTPS1 also shares sentences with these, for which no sentence is quoted: colorectal cancer (2 papers); hepatocellular carcinoma (2); leukemia (2); lung carcinoma (2); cerebral infarction (1); colon carcinoma (1); follicular lymphoma (1); genetic diseases (1); graft versus host disease (1); heart failure (1); idiopathic pulmonary fibrosis (1); lymphopenia (1); non-lymphocytic leukemia (1); Obesity (1); Primary immunodeficiencies (1); renal carcinoma (1); T-cell lymphoma (1); trypanosomiasis (1).